ARPP19 (cAMP regulated phosphoprotein 19)
Description:
Protein phosphatase inhibitor that specifically inhibits protein phosphatase 2A (PP2A). Inhibition of PP2A is enhanced when ARPP19 is phosphorylated. When phosphorylated at Ser-62 during mitosis, specifically interacts with PPP2R2D (PR55-delta) and inhibits its activity, leading to inactivation of PP2A, an essential condition to keep cyclin-B1-CDK1 activity high during M phase. May indirectly enhance GAP-43 expression (By similarity).
Synonyms: ARPP-19; ARPP-16; ARPP16; ENSAL
Tractability: PROTAC: ubiquitination databases record sites on it; its protein half-life has been measured.
Gene: Protein-coding gene on chromosome 15 (52,547,045 to 52,569,883, reverse strand). Ensembl gene ENSG00000128989.
Subcellular location: Cytoplasm
Subcellular location (Human Protein Atlas): Basal body; Vesicles; Cytosol; Nucleoli
Pathways (Reactome):
Cell Cycle: MASTL Facilitates Mitotic Progression
Gene Ontology:
Molecular function: potassium channel regulator activity; protein binding; protein phosphatase 2A binding; protein phosphatase inhibitor activity; signaling receptor binding; phosphatase inhibitor activity; protein phosphatase regulator activity
Biological process: G2/M transition of mitotic cell cycle; mitotic cell cycle; negative regulation of phosphatase activity; positive regulation of gluconeogenesis; positive regulation of D-glucose import
Cellular component: cytoplasm; nucleoplasm
Genetic constraint (gnomAD): Loss-of-function variants: 5 observed, 5.45 expected, observed/expected ratio (o/e) 0.92, 90% interval 0.47 to 1.75. That is too few expected variants to judge how well the gene tolerates losing a copy. Missense variants: 44 observed, 40.4 expected, observed/expected ratio (o/e) 1.09, 90% interval 0.85 to 1.4. Synonymous variants: 18 observed, 15.78 expected, observed/expected ratio (o/e) 1.14, 90% interval 0.79 to 1.67.
Homologues: Orthologues: chimpanzee ARPP19 (100% identical), dog ARPP19 (100% identical), pig ARPP19 (100% identical), mouse Arpp19 (99% identical), rat Arpp19 (99% identical), rat LOC100360828 (99% identical), guinea pig ARPP19 (98% identical), macaque ARPP19 (91% identical), tropical clawed frog arpp19 (81% identical), zebrafish arpp19b (81% identical), zebrafish arpp19a (74% identical), Caenorhabditis elegans ensa-1 (41% identical). Paralogues in human: ENSA (76% identical).
Diseases named in the same sentence as ARPP19 in open-access papers:
ARPP19 is named in the same sentence as 17 diseases in open-access papers, as found by Europe PMC text mining. Sharing a sentence is not in itself a finding about the gene and the disease. The quoted sentences say what the papers report.
cervical cancer (5 papers, 2014 to 2025). A primary or metastatic malignant neoplasm involving the cervix. "For instance, DLX6-AS1 accelerated the process of cervical cancer through sponging miR-16-5p to modulate ARPP19." (PMID 33902591, 2021). "This is consistent with the report that silencing ARPP-19 reduced the number of mitotic cells by 50% in the human cervical cancer HeLa cells." (PMID 25547487, 2014). "Furthermore, Xie and colleagues demonstrated that cAMP regulated phosphoprotein 19 (ARPP19) is a direct target of miR-16, suggesting that increased miR-16 production suppresses ARPP19 and enhances apoptosis in cervical cancer." (PMID 37767112, 2023).
hepatocellular carcinoma (4 papers, 2014 to 2023). A malignant tumor that arises from hepatocytes. "WAC-AS1 can regulate ARPP19 to promote glycolysis and proliferation by sponging miR-320d in hepatocellular carcinoma." (PMID 36911393, 2023). "By contrast, in hepatocellular carcinoma, WAC-AS1 regulated the glycolysis gene ARPP19 while functioning as a competing endogenous RNA (ceRNA) that inhibited the targeting of ARPP19 by miR-320d, thereby promoting glycolysis and tumor progression." (PMID 37248547, 2023). "In hepatocellular carcinoma, WAC-AS1 correlates with poor prognosis and promotes glycolysis and cell proliferation by regulating miR-320d/ARPP19." (PMID 37957698, 2023). "Expression of ARPP-19 was increased in human hepatocellular carcinoma (HCC) compared to adjacent non-tumorous liver tissues in 36 paired liver samples, and the level of ARPP-19 in HCC tissues was positively correlated with the tumor size." (PMID 25547487, 2014).
breast carcinoma (3 papers, 2015 to 2025). "Our results showed that miR-320a, upregulated by P4 through c-Myc, sensitized tamoxifen-resistant breast cancer cells to tamoxifen by targeting ARPP-19 and ERRγ." (PMID 25736597, 2015). "Thus we revealed a novel P4 elicited signaling cascade herein (P4-c-Myc-miR-320a- ARPP-19/ERRγ/c-Myc/Cyclin D1) to modulate tamoxifen-resistant breast cancer cells." (PMID 25736597, 2015).
Down syndrome (2 papers, 2014 to 2020). "Decreased levels of ARPP-19 and PKA in brains of Down syndrome and AD." (PMID 31934508, 2020).
Alzheimer disease (1 paper, 2008). A progressive, neurodegenerative disease characterized by loss of function and death of nerve cells in several areas of the brain leading to loss of cognitive function such as memory and language. "Among the genes being down-regulated in the brains of Eya3 mutants, several are reported to be down-regulated also in Alzheimer's disease, e.g. ARPP19, BIRC4, MT3, SYT1 or TTR." (PMID 19102749, 2008).
anxiety disorder (1 paper, 2024). A category of psychiatric disorders which are characterized by anxious feelings or fear often accompanied by physical symptoms associated with anxiety. "For anxiety disorders, 18 SNPs are linked to genes including CAMKMT, ARPP19, SOCS5, TNS3, VWDE, TSHZ2, and others." (PMID 39165506, 2024).
Cirrhosis (1 paper, 2014). A chronic disorder of the liver in which liver tissue becomes scarred and is partially replaced by regenerative nodules and fibrotic tissue resulting in loss of liver function. "We further examined possible associations between the levels of ARPP-19 mRNA and the clinicopathologic parameters of the HCC patients, including age, gender, etiology, maximal tumor size, histologic grade, presence of cirrhosis and serum alpha-fetoprotein (AFP) concentration." (PMID 25547487, 2014).
Fanconi anemia complementation group A (1 paper, 2019). Fanconi anemia complementation group A is a protein which in humans is encoded by the FANCA gene. "Indeed, the decrease in proliferation observed in TMEM45A-inactivated cells may be explained by the deregulation of the expression of genes implicated in G2/M transition pathway such as FANCA (Fanconi Anemia Complementation Group A) and ARPP19 (CAMP Regulated Phosphoprotein 19)." (PMID 31801939, 2019).
gastric cancer (1 paper, 2021). A primary or metastatic malignant neoplasm involving the stomach. "IGFL2-AS1 promoted gastric cancer development via a signaling axis involving the microRNA, miR-802, and cAMP-regulated phosphoprotein 19 (ARPP19), and was found to predict poor prognosis in ccRCC." (PMID 34402862, 2021).
liver cancer (1 paper, 2022). An epithelial or non-epithelial malignant neoplasm that arises from the liver. "Recent study has reported that lncRNA WAC-AS1 is highly expressed in liver cancer tissues and cell lines, and verified that WAC-AS1 can regulate ARPP19 by sponging miR-320d to promote glycolysis and tumor proliferation." (PMID 35506372, 2022).
nasopharyngeal carcinoma (1 paper, 2023). A carcinoma arising from the nasopharyngeal epithelium. "Moreover, ARPP19 overexpression was corroborated to neutralize the repressive effect of SNHG6 knockdown on the progression of nasopharyngeal carcinoma." (PMID 36874625, 2023).
cancer (9 papers, 2015 to 2023). A tumor composed of atypical neoplastic, often pleomorphic cells that invade other tissues. "Arpp19 overexpression associated with a gain of tumorigenic properties has been reported in a high number of cancers, indicating that, as expected by its PP2A-B55 inhibitory activity, it acts as an oncogene." (PMID 33266510, 2020). "The prevalent role for PP2A inhibition in AML and in other cancer types provides a strong scientific rationale for the clinical association between low ARPP19 expression and a lower risk for AML relapse newly discovered in this study." (PMID 31717978, 2019). "IGFL2-AS1 is known to regulate the expression of ARPP-19, a PP2A inhibitory protein that has been associated with several types of human cancer." (PMID 36674495, 2023). "Accordingly, there is a proven consent for targeting ARPP-19 to prevent ARPP-19—PP2A interaction to treat ARPP-19 related cancer types." (PMID 33842550, 2021). "Two additional microRNAs, miR-26A and miR-320, have been shown to be involved in Arpp19 overexpression and cancer treatment resistance." (PMID 33266510, 2020). "miR-26A down-regulation in Papillary Thyroid Carcinoma is associated with increased cell proliferation and treatment resistance, and the knockdown of Arpp19 sensitizes these cancer cells to tamoxifen." (PMID 33266510, 2020). "Thus, ARPP-19 overexpression in these cancers results in inhibited PP2A activity promoting accelerated passage through the cell cycle." (PMID 36328247, 2022). "A PP2A inhibitor protein, ARPP-19, has recently been connected to several human cancer types." (PMID 33842550, 2021). "In these cancer cells, colony formation and cell proliferation, migration, and invasion are attenuated upon miR-802 ectopic expression and this attenuation is reversed by the overexpression of Arpp19." (PMID 33266510, 2020). "This review will cover the different contributions that have recently appeared on the role of Gwl, Arpp19, ENSA, and PP2A-B55 in tumoral cascades and their misregulation in cancer." (PMID 33266510, 2020). "The discovery of the Greatwall (Gwl)/Arpp19-ENSA cascade, a new pathway specifically controlling PP2A-B55 activity, has been shown to be frequently altered in cancer." (PMID 33266510, 2020). "Increasing data identifies Gwl, Arpp19, and ENSA as proteins commonly misregulated in a high number of cancers displaying prognostic and therapeutic value." (PMID 33266510, 2020). "In cancer, the non-genomic inhibition of PP2A activity by elevated expression of endogenous PP2A inhibitor proteins (PAIPs), such as CIP2A, SET, PME1, ARPP19 and TIPRL, greatly exceeds the frequency of genetic mutations on PP2A genes." (PMID 31717978, 2019). "Of note, this study revealed a cancer-associated truncated version of MASTL, referred to as MASTL450 that displays catalytic activity, not on Arpp19 or ENSA, but on novel substrates, such as high mobility group protein A1 (HMGA1), which has been linked to the metastatic progression of cancer cells." (PMID 32640605, 2020). "Unlike Arpp19, ENSA expression appears to be less involved in cancer development and progression." (PMID 33266510, 2020).
tumor (8 papers, 2014 to 2023). "ARPP19 overexpression has been linked to tumor progression in solid cancers such as glioma and hepatocellular carcinoma but its role in AML has not been studied as yet." (PMID 31717978, 2019). "A significant positive association was observed between the ARPP-19 mRNA level and tumor diameter size (Spearman r = 0.43, p < 0.01), but not with other clinicopathologic parameters." (PMID 25547487, 2014). "Meanwhile, IGFL2-AS1 also exerted its function as a tumor promoter by regulating miR-802/cAMP-regulated phosphoprotein 19 (ARPP19) axis." (PMID 36732762, 2023). "For instance, PP2A, the downstream molecule of ARPP-19, has been reported to function as a tumor suppressor." (PMID 25547487, 2014). "WAC-AS1 regulates ARPP19 to promote glycolysis and tumor proliferation by sponging miR-320d in HCC." (PMID 36980686, 2023). "Three of the studies investigated reported on tumor tissue vs non-tumor tissue (GSE15471, GSE16515 and GSE101448), and in all these, we found an upregulation of KIAA1524/CIP2A, TIPRL, STRN and ARPP19, and a reduced expression of PPP2R1B in the tumor." (PMID 37170215, 2023). "Various studies reported that miR-26a acts as a tumor suppressor by downregulating c-MYC pathway, cAMP regulated phosphoprotein 19 (ARPP19), HOXC9." (PMID 32512882, 2020). "The current study thus assessed the level of ARPP-19 expression in human HCC and compared it to that in paired adjacent non-tumor liver tissues and examined the potential effect of ARPP-19 on cell proliferation and the cell cycle." (PMID 25547487, 2014). "Our results showed higher expression of ARPP-19 in HCC compared to that in the paired non-tumorous liver tissues, and the level of ARPP-19 was positively correlated with the tumor size." (PMID 25547487, 2014).
ARPP19 also shares sentences with these, for which no sentence is quoted: osteosarcoma (2 papers); acute myeloid leukemia (1); leukemia (1); squamous cell carcinoma (1).